MCM8 (minichromosome maintenance 8 homologous recombination repair factor)
Diseases named in the same sentence as MCM8 in open-access papers (continued):
Sharing a sentence is not in itself a finding about the gene and the disease.
large-cell lung carcinoma (1 paper, 2021). "In this study, we found that MCM7 was highly expressed in LUAD, while MCM8/10 were overexpressed in large cell lung cancer and LUSC, all of which negatively associated with patient’s OS." (PMID 33936158, 2021).
leiomyoma (1 paper, 2018). A well-circumscribed benign smooth muscle neoplasm characterized by the presence of spindle cells with cigar-shaped nuclei, interlacing fascicles, and a whorled pattern.
menopause (1 paper, 2019). Cessation of menstruation, occurring in (e.g.) the human female usually around the age of 50. "MCM8 has also been implicated in length of reproductive lifespan, menopause, and premature ovarian failure." (PMID 31649266, 2019).
myelodysplastic syndrome (1 paper, 2023). A clonal hematopoietic disorder characterized by dysplasia and ineffective hematopoiesis in one or more of the hematopoietic cell lines. "Moreover, MCM8 and MCM9 KO mice are predisposed to hematopoietic proliferation anomalies with the development with the age of myeloid tumors that are similar to myelodysplastic syndromes in humans." (PMID 36769638, 2023).
polyposis (1 paper, 2025). "Additionally, given previous reports linking biallelic MCM8 variants to CRC4 and the potential underestimation of cancer and polyposis in our case series, it may be prudent to consider biallelic MCM8 variants in cases of unexplained CRC or polyposis until further data are available." (PMID 40684266, 2025).
rectal adenocarcinoma (1 paper, 2020). "Furthermore, MCM8 was found to be 1.980- and 1.937-fold higher in colon and rectal adenocarcinoma samples respectively as compared with relevant normal tissues." (PMID 32597491, 2020).
sarcoma (1 paper, 2021). A usually aggressive malignant neoplasm of the soft tissue or bone. "Using CCLE datasets, we found that MCM8 and MCM9 were both overexpressed in che cell line of sarcoma." (PMID 34239894, 2021). "In sarcoma, most of MCM members were highly expressed in cancer tissues, except for MCM8 and MCM9." (PMID 34239894, 2021).
cancer (23 papers, 2015 to 2025). A tumor composed of atypical neoplastic, often pleomorphic cells that invade other tissues. "In TCGA Pan-Cancer Atlas dataset, insights into the somatic mutational behavior of MCM8 and MCM9 were gained through the observation of copy-number alterations in both genes." (PMID 40684266, 2025). "Given the uncertain range of phenotypic manifestations and unclear cancer risk estimates, this study aimed to delineate the molecular and clinical characteristics of biallelic germline MCM8/MCM9 variant carriers." (PMID 40684266, 2025). "Further studies are essential to accurately assess cancer risk and determine the causative role of MCM8/MCM9 deficiency in cancer predisposition." (PMID 40684266, 2025). "In the HMF cancer-specific cohort, four monoallelic MCM8 and three monoallelic MCM9 variant carriers meeting the pathogenicity-based filtering criteria were identified with CRC." (PMID 40684266, 2025). "The enhanced expression of MCM8 was found to be associated with the advanced histologic stage of malignant tumors and poor prognosis of patients." (PMID 33931059, 2021). "After variant prioritization, germline WES data analysis selecting for variants located on genes with a function compatible with cancer development yielded 2 potentially pathogenic MCM8 variants in a male patient with early-onset CRC LLS (LLS17)." (PMID 32841224, 2020). "In addition, SBS1 and SBS5—alongside SBS93 and SBS40, both of unknown origin—were the most prominent signatures in metastasized CRCs from seven individuals with monoallelic MCM8 or MCM9 variants in the HMF cancer-specific cohort." (PMID 40684266, 2025). "Develop AmNA-modified ASO (8-3419) targeting MCM8 as a cancer-specific chemosensitizer for platinum compounds." (PMID 41403730, 2025). "Due to the limited number of families with biallelic germline MCM8/MCM9 variants described so far, the complete spectrum of phenotypic manifestations and accurate cancer risk estimates remains uncertain." (PMID 40684266, 2025). "A number of studies have shown that minichromosome maintenance 8 homologous recombination repair factor (MCM8) can promote malignant tumour progression." (PMID 39031896, 2024). "The reported mutations of MCM8 in POI and cancer patients are mostly located within the AAA+ core domain (61%), suggesting the central role of the AAA+ core domain in the functional integrity of MCM8." (PMID 38858601, 2024). "MCM8 expression was positively correlated with that of DNAJC10 in LC samples from The Cancer Genome Atlas database, and DNAJC10 upregulation was also associated with poor overall survival of patients with LC." (PMID 39031896, 2024). "Knockout of MCM8 or MCM9 selectively increases cisplatin sensitivity in specific cancer cells such as HCT116 and HeLa cells." (PMID 36776764, 2023). "As for cancer, a meta-analysis of genome-wide copy number recognized the overexpression of MCM8 in a variety of human malignancies." (PMID 37710286, 2023). "MCM6, MCM7, and MCM8 collaborate with other MCM family members to promote cancer cell proliferation through cell cycle and DNA replication." (PMID 35360518, 2022). "Some cancer-related proteins were consistently changed in MNNG/HOS cells after knocking down MCM8, including the downregulation of P-Akt, CDK1, and CDK6, as well as the upregulation ofMAPK9." (PMID 33828075, 2021). "Mutations in MCM8 and MCM9 in humans are linked to premature ovarian failure (POF), amenorrhea, sterility, and cancer." (PMID 33539926, 2021). "The upstream mechanisms of MCM8 in cancer are studied poorly." (PMID 38988047, 2024). "MCM8 is also considered as a potential cancer therapeutic target." (PMID 38988047, 2024). "Additionally, numerous studies have demonstrated that MCM8 facilitates progression of various cancers." (PMID 38988047, 2024). "In tissues, high expression of MCM8 may act as a valuable prognostic indicator for different cancer therapy, consistent with gastric and cervical cancer." (PMID 36776764, 2023).
cancer (continued). "In view of the fact that cancer cells are under more pressure to replicate than normal cells due to the high growth stimulation of carcinogenesis, some studies point out that MCM8 played an essential role in the repair process of replication stress." (PMID 33931059, 2021). "Instead, several human cancer genomes show homo and heterozygous deletions in MCM9 coding regions, many missense mutations in MCM8 and MCM9, and altered expression levels that correlate with aggressive clinical features and poorer long-term survival in several human cancers." (PMID 33539926, 2021). "In addition, our study showed that MCM8 knockdown suppressed the development and progression of cancer in vivo." (PMID 33155430, 2020). "None of the family members with homozygous mutations in MCM8 or MCM9 genes had cancer at the time of investigation, but all of them were premenopausal." (PMID 26119146, 2015). "This rarity may have contributed to the absence of biallelic MCM8/MCM9 variants in the cancer-specific cohorts and could have influenced the enrichment analysis of these variants in the 100000 Genomes Project and 200000 UK Biobank." (PMID 40684266, 2025). "However, these clock-like mutational processes, commonly found in most CRCs without specific DNA repair defects and in many other cancer types, were not more prevalent in tumors from MCM8/MCM9 variant carriers than in those from our wild-type control." (PMID 40684266, 2025). "However, siRNA‐mediated MCM8 silencing could not alter the cisplatin sensitivity of normal HFF2/T fibroblasts, indicating MCM8 may act as a molecular target just in cancer cells." (PMID 36776764, 2023). "Therefore, the MCM8-9 complex facilitates DNA resection by the MRN complex during HR repair, genetic or epigenetic inactivation of MCM8 or MCM9 are seen in human cancers, and genetic inactivation of MCM8 may be the basis of a POF syndrome." (PMID 26215093, 2015). "In addition, KEGG pathway enrichment analysis indicates that MCM8/RPS15A axis also plays an important role in cell senescence and MicroRNA in cancer." (PMID 38988047, 2024). "MCM8 and MCM9, which form a stable complex, were among the most abundant proteins identified, suggesting that HORMAD1 might have a functional link with MCM8–MCM9 complex in cancer cells." (PMID 32647118, 2020).
tumor (22 papers, 2015 to 2025). "MCM8 expression level was associated with tumour stage and regional lymph node metastasis." (PMID 39031896, 2024). "The continuous measurement of tumor volume showed remarkably slower grow rate of tumors formed by RKO cells with MCM8 knockdown relative to that formed by RKO cells transfected with shCtrl." (PMID 37710286, 2023). "In vivo imaging facilitated by bioluminescence of luciferase also validated much lighter tumor burden in mice implanted with MCM8 silenced RKO cells." (PMID 37710286, 2023). "Knockdown of MCM8 in mice diminished xenografted tumor volume, which implied the critical role of MCM8 in tumor metastasis in vivo." (PMID 36776764, 2023). "In conclusion, MCM8 was identified as a tumor promotor of CRC, which is upregulated in CRC tissues compared with normal tissues and capable of promoting CRC progression through regulating cell proliferation, cell apoptosis and cell migration." (PMID 37710286, 2023). "The statistical analysis between MCM8 expression in 98 clinical specimens and tumor characteristics also showed that MCM8 was significantly upregulated in CRC and related to tumor grade." (PMID 37710286, 2023). "Based on the consideration of seeking similar tumor promotor as MCM8, several downregulated DEGs were selected as candidates, whose expression was detected in RKO cells." (PMID 37710286, 2023). "The expression level of MCM8 was found to be upregulated in CRC tissues and significantly associated with tumor grade and patients’ survival." (PMID 37710286, 2023). "Subsequently, we evaluate the correlations between MCM8 expression and composition of the tumor microenvironment as well as immunocyte infiltration ratio in HCC." (PMID 36575045, 2022). "As such, we explored the correlation between MCM8 expression and 22 tumor-infiltrating immune cells using the CIBERSORT algorithm and ssGSEA." (PMID 36575045, 2022). "The univariate Cox regression analysis demonstrated that greater tumor size (P=0.016), higher TNM stage (P=0.022), Child-Pugh class B (P<0.001), vascular invasion (P=0.006) and higher MCM8 protein level (P=0.002) were risk factors for OS in patients with HCC." (PMID 36575045, 2022). "MCM8 mRNA was found expressed in the placenta, lung, and liver, and its expression is altered in certain forms of neoplasia." (PMID 36575045, 2022). "Next, the correlation between MCM8 expression and 22 tumor-infiltrating immune cells in HCC was also investigated by employing the ssGSEA algorithm with Spearman’s analysis." (PMID 36575045, 2022). "Hereafter, in this study, we set out to verify the fact that MCM8 knockdown inhibited cell proliferation and migration, promoted cell apoptosis, arrested cell cycle, as well as suppressed tumor growth." (PMID 33931059, 2021). "MCM2, MCM3, MCM6, MCM8, MCM9, and MCM10 groups significantly varied and associated with the tumor stages." (PMID 34490114, 2021). "IHC results confirmed significantly higher expression of MCM8 in tumor tissues than in adjacent normal tissues." (PMID 33828075, 2021). "High MCM8 expression was significantly correlated with more advanced tumor grade and pathological stage." (PMID 33828075, 2021). "Lastly, nude mice were subcutaneously injected with T24 cells transfected with shCtrl or shMCM8 lentiviruses to establish a subcutaneous xenograft model, so as to further demonstrate the tumor-suppressive effects of MCM8 in vivo." (PMID 33931059, 2021). "The mRNA expression of MCM2/3/4/5/6/7/8/10 in tumor tissues was significantly higher than that in normal tissues (p < 0.05), while the expression of MCM8/9/10 in tumor tissues was lower than that of other MCMs (MCM2/3/4/5/6/7)." (PMID 34404366, 2021). "The decreased volume of xenografted tumor in MCM8 knockdown mice testified the significant role of MCM8 in metastasis in vivo." (PMID 32089988, 2020). "The volume and weight of tumours were significantly reduced in the MCM8‐knockdown group when compared with those in the control group." (PMID 33155430, 2020).
tumor (continued). "Notably, examination of the clinical samples revealed increased mRNA expression and positive staining of MCM8 in the tumor tissues compared to the normal tissues." (PMID 40095759, 2025). "Interestingly, the data from both the GSE94660 and GSE121248 datasets revealed upregulation of EP300 and MCM8 in HBV‐positive HCC tumors compared to non‐tumor tissues (LogFC > 0)." (PMID 40095759, 2025). "Furthermore, our IHC staining analysis showed that the expression of MCM8, DNAJC10 and Ki67 were all decreased in MCM8 knock down xenograft model‐derived tumours compared with control." (PMID 39031896, 2024). "Results showed that MCM8 knockdown reduced tumor volume and weight." (PMID 38988047, 2024). "This suggests that MCM8 can act as a tumor promoter in CRC and may be regarded as a promising therapeutic target for CRC." (PMID 38785984, 2024). "Moreover, MCM8 knockdown inhibited tumor growth, RPS15A expression, and phosphorylation of P38α, LYN, and p70S6K in vivo." (PMID 38988047, 2024). "MCM8 exerts tumor promotor function in multiple digestive system tumors." (PMID 38988047, 2024). "Therefore, the modified RKO cells were subcutaneously implanted into mice to demonstrate the effects of MCM8 knockdown on tumor growth." (PMID 37710286, 2023). "Moreover, as judged from the MCM8 expression in tumor tissues with different grade, it is clear that MCM8 expression increases with the severity of tumors." (PMID 37710286, 2023). "Moreover, the sections of xenografts were subjected to IHC analysis for evaluating expression of Ki-67 and PCNA as a representation of tumor growth, indicating lower proliferation activity of xenograft removed from mice implanted with MCM8 silenced RKO cells." (PMID 37710286, 2023). "In conclusion, the outcomes of our study showed the first evidence that MCM8 act as a tumor promotor in CRC, and may be a promising therapeutic target of CRC treatment." (PMID 37710286, 2023). "Altogether, these results shed light on the role as tumor promotor of CHSY1 which may possess synergistic effects with MCM8 on CRC." (PMID 37710286, 2023). "For RFS, greater tumor size (P=0.036), lower tumor differentiation (P=0.027), Child-Pugh class B (P=0.014), vascular invasion (P<0.001), without tumor encapsulation (P<0.001) and higher MCM8 protein level (P=0.029) were risk factors." (PMID 36575045, 2022). "Finally, we evaluate the correlations between MCM8 expression and composition of the tumor microenvironment as well as immunocyte infiltration ratio in HCC using CIBERSORT and ssGSEA algorithms." (PMID 36575045, 2022). "Moreover, the MCM8 mRNA levels gradually increased with the progression of tumor stages and histologic grades in TCGA database." (PMID 36575045, 2022). "In our study, high expression of MCM8 was closely related to the T and tumor stages." (PMID 34490114, 2021). "In particular, cell cycle genes such as CSNK2A1, MCM8, CDK19, KIFC1 and MCM7, among which KIFC1 was previously found to be a factor for poor prognostic and a therapeutic target associated with tumour proliferation in HCC34,35, even though its immunodulatory function has never been described before." (PMID 33431814, 2021). "MCM8 knockdown exerted anti‐tumour activity both in vitro and in vivo." (PMID 33155430, 2020). "Moreover, MCM8 may be correlated with different compositions of the tumor microenvironment and immunocyte infiltration ratio in HCC." (PMID 36575045, 2022). "On the other hand, in support of their roles as a tumor promoter, several recent studies have suggested that MCM2-7, MCM8 and MCM10 were overexpressed in hepatocellular carcinoma." (PMID 33931059, 2021). "We then verified the expression level of KMT2C, ASXL1, and MCM8 in CCA using the GEPIA database and found that all of the three genes, especially ASXL1 (p < 0.05) and MCM8 (p < 0.05), were overexpressed in tumor tissues." (PMID 32010606, 2019).
tumor (continued). "Knocking down MCM8 expression in CRC cells could restrain cell growth and cell motility while promoting cell apoptosis in vitro, as well as inhibit tumor growth in xenograft mice model." (PMID 37710286, 2023). "DNA methylation of MCM8 in HCC tissues was lower than in adjacent normal liver tissues, and further analyses revealed that DNA methylation of MCM8 gradually decreased with the tumor stages and histologic grades increased." (PMID 36575045, 2022). "For RFS, vascular invasion (HR (95%CI) 2.227(1.282-3.869), P = 0.005), without tumor encapsulation (HR (95%CI) 0.246(0.145-0.415), P <0.001) and higher MCM8 protein level (HR (95%CI) 1.657(1.002-2.741), P = 0.049) were independent risk factors." (PMID 36575045, 2022). "However, MCM8 or MCM9 defects may not always be linked with a MMR-deficient or MSI-positive tumor." (PMID 32841224, 2020). "Moreover, it was demonstrated that MCM8 may regulate the expression of CHSY1 through affecting its NEDD4-mediated ubiquitination, both of which synergistically execute tumor promotion effects on CRC." (PMID 37710286, 2023). "Based on the RNA screening performing on CRC cells with or without MCM8 knockdown and the following IPA analysis, CHSY1 was identified as a potential target of MCM8 in CRC, whose expression was also found to be higher in tumor tissues than in normal tissues." (PMID 37710286, 2023). "As expected, in our report, the expression of MCM8 and MCM9 was not significantly higher in EC and was even lower in the tumor tissue, but MCM10 was highly expressed in tumors." (PMID 34859821, 2021).
digestive system cancer (1 paper, 2024). A primary or metastatic malignant neoplasm involving any part of the digestive system. "To date, there have been few reports of MCM8 in digestive system cancers." (PMID 38988047, 2024).
MCM8 also shares sentences with these, for which no sentence is quoted: endometriosis (2 papers); lung adenocarcinoma (2); adenoma (1); anemia (1); benign tumors (1); cervical cancer (1); clear cell carcinoma of the cervix (1); colonic adenomas (1); colonic polyps (1); endometrial endometrioid adenocarcinoma (1); endometrial mixed adenocarcinoma (1); endometrial serous adenocarcinoma (1); glioblastoma multiforme (1); hypothyroidism (1); immune dysfunctions (1); keloid (1); liver cancer (1); metastatic melanoma (1); myeloid tumors (1); Onset (1); osteoporosis (1); rectal polyps (1); Sertoli Cell-Only Syndrome (1); spermatogenic failure (1); uveal melanoma (1).